IL6 (interleukin 6)
Diseases named in the same sentence as IL6 in open-access papers (continued):
Sharing a sentence is not in itself a finding about the gene and the disease.
tumor (continued). "IL‐6/STAT3 activation by splice variant ΔNp63 results in the stabilization of hypoxia‐inducible factor 1α, the secretion of VEGF and angiogenesis in OS tumours." (PMID 33382511, 2021). "Inflammatory cytokines (notably interleukins IL-1, IL-6, and TNFα) released from tumor cells induce CRP protein production in hepatocytes." (PMID 34830745, 2021). "The increasing concentration of IL-6 can stimulate an inflammatory response and can lead to the domination of the tumor immune rejection processes over tolerance." (PMID 33794894, 2021). "In recent years, tumor cells have been found to form pre-metastatic niches in bone before metastasis by secreting factors such as interleukin-6 (IL-6), parathyroid hormone-related protein (PTHrP), and matrix metalloproteinases (MMPs)." (PMID 34830862, 2021). "Tumors are rich in IL-6 and IL-10, and the tumor-derived TLR-2 ligand versican can induce the overexpression of IL-6 and IL-10 receptors on DCs." (PMID 34290401, 2021). "Overall, these data show that inhibiting tumor-NLRP3 alone is sufficient to reduce IL-6/STAT3 activation, resulting in the reduction of immunosuppressive gene expression in PMN-MDSCs." (PMID 34531850, 2021). "Several major pro-tumor activities, including growth, invasion, and angiogenesis, have been identified to be closely correlated with IL-6 overexpression." (PMID 34497832, 2021). "IL6 is a pleiotropic cytokine upregulated in different tumor types, and it can depict several transcriptional programs." (PMID 34422669, 2021). "TAMs can also secrete cytokines and chemokines, such as IL-6 and IL-8, which play significant roles in carcinogenesis, tumor malignancy, and tumor invasion." (PMID 34439379, 2021). "This tumor microenvironment produces various factors such as interleukin-6 (IL-6), TNF, and TGF, all of which stimulate a transient EMT to promote cancer progression, invasion, and metastasis." (PMID 34064322, 2021). "In contrast, iCAF are localized distant from the tumor, express low α-SMA levels and exhibit rather tumor-promoting and immunosuppressive properties by secreting inflammatory cytokines, like IL-6, CXCL12 and Granulocyte-Colony stimulating Factor (G-CSF)." (PMID 34638420, 2021). "Accordingly, it was shown that tumour vascularisation in murine HCC models is enhanced by IL-6 trans-signalling and thereby further promoting hepatic tumourigenesis." (PMID 34047814, 2021). "TG2 expression and downstream IL-6 (Interleukin-6) production have been profoundly correlated with primary tumor growth, peritoneal spreading, distant metastasis and resistance to standard cytotoxic agents." (PMID 34277422, 2021). "Spatial intratumoral heterogeneity was observed for IL6 expression within the tumor mass in four out of five patients." (PMID 34422669, 2021). "There is evidence from animal studies that TLR5 signaling at mucosal surfaces promotes systemic inflammation dependent upon tumor cell- and leukocyte-derived IL-6, and involves MDSC and gamma-delta T cells, driving progression of extra-intestinal cancers." (PMID 35048056, 2021). "Regarding soluble factors, interleukin 6 (IL6) production by CAFs promotes DCIS invasion through the induction of cathepsin B expression in tumor cells." (PMID 34201840, 2021). "Osteoblastogenesis is not only inhibited by tumor-derived factors due to inactivation of pivotal signaling pathways or by induction of osteoblastic and osteocytic apoptosis as shown for Dickkopf-1, IL-6 and TNF-α." (PMID 34064859, 2021). "Cohorts of IL6+/+;Eμ-myc, IL6+/-;Eμ-myc and IL6-/-;Eμ-myc mice were generated and monitored for overall survival and tumor development." (PMID 33651821, 2021). "Cancer-associated fibroblasts (CAFs) are one of the major sources in the tumor microenvironment to secrete IL6 and IL825–27." (PMID 34290255, 2021). "Inhibition of XBP1 in TAMs downregulated the expression of pro-tumor cytokines, such as IL-4, IL-6, MMP2 and VEGFA." (PMID 34667145, 2021).
tumor (continued). "We also found increased expression of Il-1β, Il-6, and Ifn- γ in tumor stroma from Trpa1-/- group compared to wild type animals." (PMID 34041030, 2021). "The ELISA results in animal model showed a positive correlation of plasma IL-6 level with tumor size." (PMID 34093869, 2021). "In our study, the data shows that the crosstalk between cancer cells and macrophages in muscle tissues is that tumor cells secrete IL-6 inducing macrophages to up-regulate MMP12." (PMID 34863141, 2021). "Because IL-6 has been shown to promote lipolysis, we evaluated tumor effects on adipose tissue wasting." (PMID 33851955, 2021). "Primary tumours can activate resident fibroblasts both in lung and liver, which promote metastatic cancer growth by secreting proinflammatory cytokines such as IL-6 and IL-8." (PMID 35006432, 2021). "Overexpression of CRYβB2 increases invasive cellular behaviors, tumor growth, IL6 production, immune cell chemoattraction, and the expression of metastasis-associated genes." (PMID 34947885, 2021). "It was demonstrated, that IL-6 contributed to the acceleration of tumor progression and increased migration of CRC cells." (PMID 35008550, 2021). "In the presence of both C-7 and autologous PBMC, increased levels of IL-10 and IL-6 were found compared to the tumor alone (p = 0.002 and p = 0.004, respectively) and the “tumor + C-7” conditions (p = 0.032 and p = 0.025, respectively)." (PMID 34771609, 2021). "Densitometry analysis showed that five cytokines, IL-4, AXL, IL-1β, IL-9, Exotaxine-2 and IL2, were upregulated, and two cytokines, PF4 and IL-6, were downregulated in the tumor environment of JEG3-Sh-NLRP7 cells." (PMID 34203890, 2021). "The astrocyte-tumor interaction increases the expression of receptors for IL-6 and its subunit gp130 and decreases the receptors for TNF-α and IL-1β on HARA-B metastatic lung squamous carcinoma cells." (PMID 33466236, 2021). "In cancer, IL-6 drives proliferation, survival, invasiveness, and metastasis of tumor cells, while strongly suppressing the anti-tumor immune response." (PMID 34394118, 2021). "In our study, in agreement with the tumor-promoting effect of the ALDH1L1 loss, both NF-κB and IL-6 were strongly elevated in Aldh1l1 KO livers compared to WT livers." (PMID 34203215, 2021). "In vitro studies have demonstrated that reovirus administration induces DC maturation, stimulates proinflammatory cytokine production, including IFN-alpha, TNF-alpha, and IL-6, and increases NK cell cytolytic activity on tumor cells." (PMID 34976006, 2021). "PER1 can promote cell apoptosis and expression of TNF-α, IL-6, and programmed death 1 (PD-1)/PD-L1, and inhibit tumor invasion and TUBB2B gene expression." (PMID 34220965, 2021). "L-Kyn mediated AhR activation promotes tumor growth with elevated levels of inflammatory cytokines (IL-6, IL-8, and IL-1β) and a decreased frequency of infiltrating cytotoxic CD8+ T cells in TME." (PMID 34867973, 2021). "Multiplex chemokine and cytokine quantification showed a marked decrease of the neutrophil chemoattractant CXCL1, IL6, and the tumor growth supporting TGFβ and VEGF in plasma-treated compared to untreated co-culture settings." (PMID 34064000, 2021). "Clinical evidence had shown that IL-6 in tumor biopsy tissue is an inflammatory marker in the diagnosis of CAC, and high levels of IL-6 in tumor tissue and serum correlate with weight loss and muscle atrophy." (PMID 34863141, 2021). "Their interaction with the BMDMs and tumor cells in the collagen-I matrix increased production of GM-CSF, G-CSF, IL-6, CCL2, CCL3, CCL4 and CCL12, and reduced production of IFN-β1, LIF, VEGF, CCL17, CXCL5 and CX3CL1." (PMID 34572807, 2021). "Mechanistically, we found that AhR expression contributed to the secretion of Interleukin-6 (IL-6), thereby promoting tumor cells proliferation through the STAT3 and NF-kB/TIM4 signals." (PMID 34657635, 2021).
tumor (continued). "Tumor cells or TAMCs produce GM-CSF, G-CSF, and IL-6 that drive CCAAT/enhancer binding protein beta (C/EBPβ)-dependent myelopoiesis from myeloid progenitor cells in human and mouse bone marrow, generating MDSCs." (PMID 34359674, 2021). "Inflammatory cells related to the tumour and tumour cells related to tumorigenic inflammatory cytokines, such as tumour necrosis factor, interleukin (IL) IL-1, IL-6, and vascular endothelial growth factor can induce invasion, growth, and tumour metastasis." (PMID 33740951, 2021). "Interleukin-6 (IL-6) is a multi-functional pro-inflammatory cytokine that has crucial roles in tumours progression through growth-promotion, anti-apoptotic activity, and modulation of immune function." (PMID 34582655, 2021). "Using this approach, IL-6 and its receptor were found to be good candidates for mediating the cross talk between tumor cells and HSPCs." (PMID 34140316, 2021). "STAT3 hyperactivation in tumor cells can occur as a result of increased IL-6 levels in the serum and/or the tumor microenvironment, or as a result of loss-of-function mutations affecting STAT3 negative regulators." (PMID 35155571, 2021). "IL6 levels decreased after cHL treatment to pre-diagnosis levels, pointing out the relation between the size of the tumor and the levels of IL-6." (PMID 35008292, 2021). "Since IL6 is a cytokine that can be produced either by immune or tumor cells, we decided to analyze which cells were responsible for the high IL6 expression detected in ESCC." (PMID 34422669, 2021). "In the tumor microenvironment, IL-6/JAK/STAT3 signaling acts to drive the proliferation, survival, invasiveness, and metastasis of tumor cells, while strongly suppressing the antitumor immune response." (PMID 33540700, 2021). "Whereas the IL-6 impact is to sustain expansion of MDSCs, the IL-8 contribution is to attract these tumor suppressor cells at MME." (PMID 35011682, 2021). "In conclusion, we found that exosomes exhibit increased secretion of IL-1β, IL-6, and IL-8 in CAFs, promoting fibroblast activation, stimulation of Wnt signaling pathway, tumor cell proliferation and migration, and cancer growth." (PMID 34261453, 2021). "Tumor cell undergoes epithelial to mesenchymal transition (EMT) through secretion of IL-6, IL-8, GRO, GM-CSF, VEGF, and angiogenin." (PMID 34220337, 2021). "The key molecules stimulating tumor growth and invasion induced by these bacteria include IL-6, cyclin D1, TNFα, MMP9 and heparanase." (PMID 33823861, 2021). "For example, CAFs‐derived IL‐6 can activate the STAT3 pathway to promote EMT of tumor cells, thereby facilitating metastasis." (PMID 34977870, 2021). "It was also recently reported that the leukemia inhibitory factor (LIF) secreted by the tumor induces changes in the expression of AT, as well as serum levels of IL-6 and leptin, acting in a JAK-dependent manner." (PMID 33557173, 2021). "IL-17A enhanced tumor growth in vivo via induction of IL-6, activating oncogenic transcription factor STAT3 and stimulating pro-survival and pro-angiogenic tumor genes." (PMID 35008550, 2021). "IL-6 plays a role in recruiting immune cells within the tumor microenvironment and stimulates the production of pro-inflammatory cytokines." (PMID 34445405, 2021). "Cytokine-mediated cross-talk, led by IL-6, has been reported to play a role in tumor-elicited inflammation and the development of CSCs." (PMID 34299605, 2021). "Both transwell and migration assays showed that NPTX2 overexpression markedly promoted tumor cell invasion and migration, while these promoting effects were also reversed after IL-6-neutralizing antibody treatment." (PMID 33768003, 2021). "Upregulation of IL-6 and related pathway mediators as well as the anti-tumor efficacy of IL-6 pathway inhibition have been reported in OCCC5,6,19,20." (PMID 33833265, 2021).
tumor (continued). "In the same vein, inhibition of autophagy in pancreatic non-tumor stellate cells restrains expression of the pro-migratory cytokine IL-6 and of the extracellular matrix proteins in pancreatic cancer, limiting tumor migration and invasion." (PMID 34944758, 2021). "If the patients were grouped by tumor size (± 7 cm) and studied by Kaplan–Meier analyses, both IL-6 (p = 0.014) and IL-27 (p = 0.001) predicted recurrence among patients with large tumors (diameter > 7.0 cm)." (PMID 32621022, 2021). "First, in a model of SOX4 upregulation via TGFβ-1, since this cytokine is produced in higher levels in MM, by both tumor cells and BMSCs, exerts inhibitory effects on normal B-cell proliferation and Ig secretion, and regulates the secretion IL-6 in MM cells." (PMID 34945712, 2021). "For example, IL-6, VEGF, CCL22 and/or PGE2 produced by tumor cells recruited tumor-associated macrophages, which in turn produced IL-23 and maintained suppressive Treg activity in the TME." (PMID 33418929, 2021). "Tumor cells produce inflammatory cytokines, such as tumor necrosis factor α and interleukin (IL)-1 and -6, and IL-6 is a major stimulator inducing CRP synthesis." (PMID 34548054, 2021). "The prominence of IL-6 signalling in the liver as well as TGFβ-driven IL-11 signalling in supporting primary tumour growth and metastasis in preclinical models suggest that these cytokines play important roles in the outgrowth of hepatic metastases." (PMID 33669775, 2021). "By changing the microenvironment of tumor tissues, IL-6 promotes the abnormal proliferation of normal tissue cells and expression of peripheral vascular genes, leading to the development and metastasis of malignant tumors." (PMID 33495421, 2021). "TAMs are a population of pro-inflammatory cells that promote tumor progression through cytokines and chemokines like IL-23, IL-6, IL-12, and TNF-α." (PMID 34778068, 2021). "The most aggressive cachexia was associated with human IL-6 in the mice, pointing to a central role for IL-6 derived from malignant cells in this third passage of the patient tumor fragments." (PMID 33851955, 2021). "IL-6 is associated with an aggressive PCa phenotype by inducing VEGF, promoting tumor cell proliferation, suppressing apoptosis, and driving Th cell differentiation of regulatory Th cells." (PMID 34604038, 2021). "The activation of IL-6/JAK2/STAT3 signaling pathway plays an active role in tumor growth and progression." (PMID 34881181, 2021). "Pedersen and colleagues found that exercise led to an epinephrine-induced mobilization and redistribution of IL-6-sensitive NK cells to the tumor site." (PMID 33806053, 2021). "TGF-β and IL-6 are related to tumor growth and/or immunosuppression and were increased in the presence of CAFs." (PMID 34408230, 2021). "The upregulation of cancer-promoting inflammatory cytokines (host and tumor-secreted), such as NF-κB, COX-2, IL-1, IL-6, TNF-α, and IFN-γ, is strongly associated with STAT3 and AKT signaling activation in oral squamous cell carcinoma in vitro." (PMID 34950252, 2021). "Another study in cholangiocarcinoma showed that tumor cell-derived extracellular vesicles can “educate” MSCs to induce local microenvironmental changes that facilitate tumour cell growth via IL-6/STAT-3 signaling pathway." (PMID 34513701, 2021). "IL‐6 is a common cytokine in the TME, and tumor-associated macrophages, granulocytes, fibroblasts, and cancer cells are all primary sources of IL‐67." (PMID 34131122, 2021). "Previous studies report that HIF1 complex and IL-6/STAT3 signaling pathway plays a crucial role in tumor angiogenesis, and STAT3 Y705 phosphorylation modulates IL-6/STAT3 signal pathway activation." (PMID 34753906, 2021). "A proteomic screen of tumor- conditioned medium integrated with the scRNA-seq data analysis revealed that the interleukin 6 (IL-6)–IL-6 receptor axis is highly active in HSPC-derived MDP cells." (PMID 34140316, 2021).
tumor (continued). "It has been shown that IL-1ß in the MM microenvironment stimulates the production of IL-6, which is the main factor in tumour survival and proliferation." (PMID 33808304, 2021). "The activation of STAT3 in OS by IL-6 is an important mechanism in OS tumor progression and metastasis." (PMID 34681692, 2021). "Both IL-6 and IL-8 are considered “oncogenic cytokines,” as they are able to cause EMT, stimulate angiogenesis and tumor growth, disrupt cell–cell communication, impede macrophage function, and promote epithelial and endothelial cell migration and invasion." (PMID 35047997, 2021). "In the case of inflammation, necrosis, or immune cells stimulated by tumor cell antigens, the secretion of IL-6 increases, which reflects an increase in bacterial colonization in tissues." (PMID 35010211, 2021). "Interleukin-6 (IL-6)/Janus kinase (JAK)-2/STAT3 signaling has been widely studied in anti-tumor therapy and participates in the differentiation of osteoblasts." (PMID 33816498, 2021). "The administration of ADSC-derived microvesicles determined a dramatic reduction in the tumor cell secretion of pro-tumorigenic cytokines, such as IL-6, IL-8, GRO-alpha, and VEGF." (PMID 34440886, 2021). "Fat loss was proportionate to IL-6; both circulating IL-6 and fat wasting were halved by elimination of IL-6 from tumor cells." (PMID 33851955, 2021). "Through soluble factors, including IL-6, PSCs induce a feedback response in tumor cells which are also metabolically activated." (PMID 34771503, 2021). "The high expression of IL-6 in cocultures of fibroblasts and tumor cells compared to tumor cell monocultures is noteworthy." (PMID 33807441, 2021). "The Hojman group also reported an IL6-dependent mechanism that activates the innate immune defense upon exercise to control tumour growth." (PMID 34359731, 2021). "Tumor cell-derived exosomes enhance the secretion of prostaglandin E2, TGF-β, and IL-6 in myeloid cells, resulting in a strong immunosuppressive environment in tumor lesions." (PMID 33828985, 2021). "The pro-inflammatory cytokines, such as interferon (IFN)-ɤ, tumor necrosis factor (TNF)-α, and interleukin (IL)-6, are well known to be key inducers for PD-L1 expression at the transcriptional level in tumor tissues." (PMID 34577564, 2021). "IL-6 also has additional roles in mediating tumour cell invasion by upregulating the expression of MMPs and fascin-1." (PMID 33803414, 2021). "The level of IL-6 is a marker for stress responses that reflects the degree of inflammation and tissue injury and is closely correlated with tumor occurrence and development." (PMID 34300310, 2021). "In particular, the presence of tumor derived inhibitory molecules such as interleukin (IL-6, 10), transforming growth factor beta (TGFβ) and VEGF produced by the tumor negatively impact the growth, maturation and differentiation of DCs." (PMID 34268109, 2021). "CD10-positivity correlated with tumor progression and chemoresistance, through persistent NF-κB activation and resultant IL-6 and IL-8 secretion." (PMID 33806802, 2021). "In CAC mouse models, IL-6 ablation reduced tumor formation and mice injected with recombinant IL-6 had increased tumor load." (PMID 34884543, 2021). "On this step of our research, we get intermediate results which showed that the presence of natural polyphenol in the cell culture rises the production of IL-6 which plays an important role in tumor suppression." (PMID 33794894, 2021). "We have also assessed IL-6, a proinflammatory cytokine secreted by tumor cells and fibroblasts, involved in angiogenesis." (PMID 34178955, 2021). "We showed that anti-IL-6 treatment reduced the levels of MDPs in the BM along with M2 macrophages in the lungs of met-high tumor-bearing mice, suggesting that MDP-derived macrophages serve as key promoters of metastasis formation." (PMID 34140316, 2021).